IGF1R (insulin like growth factor 1 receptor)
Diseases named in the same sentence as IGF1R in open-access papers (continued):
Sharing a sentence is not in itself a finding about the gene and the disease.
cancer (continued). "Although we did not detect changes in Igf1r expression levels, IGF1R becomes phosphorylated and activated in epithelial plastic cancer cells, suggesting the involvement of this pathway in the EMP acquisition." (PMID 39075581, 2024). "The physiological and clinical relevance of adhesion-enhanced IGF-1R internalization and Golgi accumulation in cancer cell lines and fibroblasts are supported by the IGF-1R staining profile in TNBC tissue compared to nontumor breast tissue." (PMID 39608716, 2024). "This reduction in IGF1-R levels may explain the reduced proliferation and invasion ability of MCF7 cells, aligning with previous reports linking increased IGF-1R activity to cancer cell proliferation, migration, and invasion." (PMID 39576770, 2024). "The activation of IGF-1R by insulin triggers several signaling pathway, including PI3K/AKT, MAPK, JAK/STAT, Sarcoma (Src), and focal adhesion kinase (FAK), all of which collectively enhance cancer cell proliferation, survival, and migration." (PMID 39290325, 2024). "Analysis of Igf1 and Igf2 expression levels showed that epithelial plastic cancer cells did not induce the expression of these factors, suggesting a paracrine activation of IGF1R." (PMID 39075581, 2024). "Furthermore, another study found that cancer cells were sensitized to cisplatin upon IGF-1R inhibition, which can occur through IGF-1R inhibitors or siRNA-mediated IGF-1R suppression." (PMID 38540176, 2024). "Moreover, several confirmed gender-related carcinogenic genes exhibit completely different distributions in male and female cancer samples, such as PIK3CA, NF1, EIF1AY, IGF1R, NRAS, KDM5D, UTY, and PPP6C." (PMID 39541191, 2024). "Studies have demonstrated that MTFs, such as human epidermal growth factor receptor (HER), fibroblast growth factor receptor (FGFR), β-catenin, Notch, insulin-like growth factor 1 receptor (IGF-1R), and insulin receptor (IR), play critical roles in tumorigenesis and cancer progression." (PMID 39404930, 2024). "The ligands for IGF1R (IGF1 and IGF2) are differentially expressed across pediatric cancers." (PMID 39510293, 2024). "Regarding cancer therapy, higher concentrations of nuclear IGF1R are not only correlated with lower survival rates in metastatic colon cancer patients, but also observed in drug-resistant colon cancer cell lines." (PMID 39404930, 2024). "Of note, IGF1R and ERBB2 drug combinations are already being investigated in the context of cancer." (PMID 38585651, 2024). "IGF1R tyrosines (Tyr)1250/1251 phosphorylation is required for the formation of a complex containing IGF1R, β1 integrin and the scaffolding protein RACK1, a crucial event sustaining the turnover of focal adhesions and cancer cell migration." (PMID 38892104, 2024). "Ongoing trials with Gh1r/Igf1r antagonists will reveal their potential in this therapeutic approach, initiated from the clinical observation that LS patients do not develop cancer." (PMID 38255007, 2024). "Other evidence indicated that the IGF1R inhibitor PPP affected autophagy and improved the therapeutic efficacy of PD-1 blockade in cancer-bearing mice, underscoring the capacity of the IGF1R antagonist to enhance chemoimmunotherapy efficacy in preclinical models." (PMID 38892104, 2024). "Our research suggests that Paromomycin may effectively inhibit GBM by targeting HDAC1 to regulate IGF1R SUMOylation, potentially opening new avenues for GBM treatment and inspiring exploration of similar mechanisms in other cancer types." (PMID 39723246, 2024). "Focusing on the insulin growth factor 1 receptor (IGF1R), a receptor tyrosine kinase that mediates growth factor signaling in various tissues and cancers, ZNRF3*IGF1R bispecific antibodies showed clearance up to 80% with specificity for CRC both in vitro and in vivo." (PMID 37592990, 2023). "Cancer cells were sorted using anti-FXYD3 and anti-NRP1 or anti-IGF1R antibodies." (PMID 37966117, 2023).
cancer (continued). "The IGF1R is commonly expressed in human tumors leading to a mitogenic response to physiological concentrations of IGF1, and both the PI3K/Akt pathway and mTOR are commonly activated in cancers." (PMID 37686596, 2023). "Furthermore, we treated cells with cisplatin, ME, or both, and the expression of cancer pathway factors was assessed, including HSP90AB1, IGF1R, p-H2AX, MYC, and PTEN." (PMID 37180757, 2023). "Particularly, IGF-1 binds to IGF-1R, a tyrosine kinase receptor, which activates its downstream signal effectors, comprising Ras/Raf/ERK and PI3K/Akt/mTOR, known to be involved in cell growth, proliferation, and in various types of cancers." (PMID 37509120, 2023). "Although anti-IGF1R monoclonal antibodies and IGF-IR inhibitors have shown potent anticancer effects in preclinical models, clinical trials of these agents have been mostly disappointing in unselected cancer patients." (PMID 36774408, 2023). "Although a couple of clinical trials examining combination treatment regimens remain active, no IGF-1R-targeting agent has yet been approved for use in cancer." (PMID 37858153, 2023). "Overexpression of IGF-1R can activate various downstream signaling pathways, such as PI3K/AKT, MAPK/ERK, EP2/EP4, and RAS/RAF/ERK, which play a key role in the propagation and apoptosis of malignant tumors." (PMID 36768298, 2023). "Interestingly, HER3 has been shown to be able to interact with MET, IGF-1R, or FGFR3 in various human cancers." (PMID 37716943, 2023). "Furthermore, MP subtype cancer cells show high sensitivity to inhibition of the IGF1/IGF1R pathway, indicating specific therapeutic implications of targeting the IGF1/IGF1R pathway in specific GC patients." (PMID 36774408, 2023). "As well as interacting with FGF to activate FGFR, αKlotho was initially found to downregulate signaling via insulin-like growth factor 1 receptor (IGF-1R), and this may contribute to its effects against some types of cancer." (PMID 37958253, 2023). "In this research, we measured a significant miR-15b-dependent regulation of Igf1r in M6 cells (carcinoma) but not in the metastatic lines MDA-MB-231 and M6C." (PMID 37686596, 2023). "Substantial efforts have been made to produce anti-cancer therapeutics that target components of IGF-1 signaling, which has resulted in the development of three major classes of inhibitors: anti-IGF-1R monoclonal antibodies, dual IR/IGF-1R tyrosine kinase inhibitors, and IGF neutralizing antibodies." (PMID 36556357, 2022). "Although activation of the IGF-1R signals results in increased glycolysis, proliferative cancer cells take up more glucose than non-proliferating cells." (PMID 36568212, 2022). "Pan-cancer analysis has shown an activating IGF-1R hotspot non-frameshift insertions, which were significantly enriched in AdCC." (PMID 36499216, 2022). "In a study, independent of the insulin-like growth factor-1 receptor (IGF-1R) pathway, it interfered with microtubule dynamics to decrease cancer." (PMID 36555406, 2022). "Since Uc.416+A stimulates cell proliferation in culture, it was proposed that low miR-153 expression in GC may contribute to cancer progression by upregulating Uc.416+A which, in turn, decreases IGFBP-6, allowing enhanced IGF-dependent activation of IGF1R." (PMID 35597813, 2022). "As ECM-CAFs originate from resident liver fibroblasts, it is interesting to note that in hepatocytes, Wnt/β-catenin signaling can synergize with insulin signaling through IGF1R, LRP5, and LRP6 34, which were concomitantly enriched in ECM-CAF-cancer cell LR interactions." (PMID 36438498, 2022). "Nevertheless, in other cancer patients, anti-IGF-1R monoclonal antibodies have no significant therapeutic effect." (PMID 35680570, 2022).
cancer (continued). "IRS2 is an insulin-like growth factor-1 receptor (IGF-1R) and insulin receptor signaling transmitter, which may be involved in the PI3K-AKT pathway, leading to the occurrence and progression of malignant tumors and inhibition of apoptosis." (PMID 36277284, 2022). "Therefore, using the tyrosine kinase inhibition of EGFR and IGF-1R induces the “BRCAness” and HRD phenotypes in breast and ovarian cancers, leading to PARPi sensitivity in the cancer cells." (PMID 36497275, 2022). "It is conceivable that IGF1R signaling induces ACBD3 expression, which would increase the pool of available GLUT4-containing vesicles and therefore increase glucose import and energy for the proliferating cancer cells, propagating the Warburg effect." (PMID 36012147, 2022). "These investigations were carried out using cells derived from human breast epithelium, as the control MCF-10a non-tumorigenic cells and the MCF-7 cancer cells, both of which express IGF-1R." (PMID 34299089, 2021). "However, the stronger colocalization of IGF-1R and PCNA is correlated to the higher overall survival in cancer patients." (PMID 34671219, 2021). "The same seems to be true for PDAC: Although former studies demonstrated decreased survival for PDAC patients with elevated IGF1R expression, IGF1R inhibitors did not improve prognosis of patients with this cancer entity." (PMID 34638472, 2021). "Furthermore, using the qRT-PCR and WB analysis, we discovered that the mRNA and protein levels of IGF1R were remarkably upregulated in CRC tissues and cell lines compared with that in non-cancer tissues and NCM460 cells, respectively." (PMID 34093664, 2021). "To investigate this hypothesis, we performed a Co-IP experiment to determine if IGF-1R and PKM2 bind to HSP90 in cancer cells." (PMID 34359752, 2021). "AR, IGF1R, PDGFRB, PIK3R1, and SUFU involved in KEGG pathways in cancer." (PMID 34208639, 2021). "Since the IGF axis could contribute to cancer progression and invasion, it is now widely accepted that aberrant methylation of IGFBP7, IGFBP-4, IGFBP-3, IGF-1R, IGF-1, and IGF-II promoters could be a potential factor in various common human cancers." (PMID 33768092, 2021). "Moreover, the IGF1R pathway is critical for EMT induction/maintenance and the expansion of cancer stem-like cells." (PMID 33917482, 2021). "It is important to mention that there are circRNAs—for instance, circ_0002577 and circ-RUNX1—which increase the expression levels of IGF1R and IGF1, respectively, leading to enhanced PI3K/AKT signaling activity, elevated cancer cell proliferation rate, and EMT." (PMID 34205978, 2021). "Insulin-like growth factor 1 receptor (IGF1R) was found to show expression-driven dependency by cancer cells of the ovary (R = −0.6, FDR = 6.7E − 3) and lung (R = −0.35, FDR = 0.04); in both cancer cohorts, we also found high IGF1R overexpression rates and hyperphosphorylation of IGF1R p.T1366." (PMID 34552204, 2021). "IGF1 receptor (IGF1R) is able to mediate IGF-1 action, and the IGF1R signaling pathway is closely related to the occurrence, development, and metastasis of tumors, which is an important indicator for clinical cancer diagnosis and prognosis." (PMID 34761108, 2021). "Dysregulation in activity of EGFR, IGF‐1R, and VEGFR is highly correlated with a lot of cancers." (PMID 33783993, 2021). "Moreover, it has been shown that IGF1R inhibition enhanced pro-apoptotic effects of GSI, thus supporting the rationale for combinatorial IGF1R and Notch targeting in this type of cancer." (PMID 34680255, 2021). "Cancer cells without any cytoplasmic IGF1R immunostaining (c-IGF1R 0) were observed in 157 (98.1%) samples." (PMID 34638472, 2021). "IGF1R and INSR genes are direct targets of BRD4 in several cancer models." (PMID 34440844, 2021). "Furthermore, high levels of SOX2 expression were found to be due to elevated levels of the IGF/IGF-1R signaling downstream proteins Akt and mTOR, which subsequently elevated HCC cancer stemness characteristics." (PMID 33669204, 2021).
cancer (continued). "Together, these results suggest that PKM2 plays a crucial role in cancer cell growth and survival as a non-metabolic protein by promoting IGF-1R/AKT signaling." (PMID 34359752, 2021). "Finally, IGF1R and HIF1A genes enriched in Cancer pathways were closely related to the occurrence and development of HBV-related HCC." (PMID 33863948, 2021). "The expressions of IGF-1 and IGF-1R were correlated with TMB and MSI in some cancer types." (PMID 34804946, 2021). "Further research suggests that this response escape is not due to the failure of IGF1R blockade, but to the recruitment of macrophages, fibroblasts and cancer cells blocked by IGF1R." (PMID 34335947, 2021). "MET, IGF-1R, and FGFR pathways are conserved across multiple cancer cell lines in response to different agents, and pharmacological targeting of these pathways may be a viable direction in combination therapy treatment." (PMID 33712615, 2021). "Despite the vast majority of studies originally focused on the specific role of the IGF1R, it is now clear that expression or functional alterations of all components of the IGF axis are important factors in contributing to IGF1R action in cancer." (PMID 33673232, 2021). "In certain cancer cells, binding of IGF-1 to IGF-1R could activate some signaling pathway and then promote oncogenic effect." (PMID 34175839, 2021). "IGF-1R is a plasma membrane receptor with tyrosine kinase activity, whose inhibitors have been used to treat carcinoma cell lines, with a strong non-proliferative effect." (PMID 34239447, 2021). "The precise mechanisms of IGF-1R import into the nucleus of normal and cancer cells are still unclear because the IGF-1R does not have a nuclear localization sequence (NLS)." (PMID 33584548, 2020). "Nuclear IGF-1R was first detected in hamster kidneys and later in cancer cells and highly proliferative non-malignant tissues." (PMID 33511137, 2020). "Based on our limited analysis so far and on the literature from other cancers, one explanatory hypothesis is that both RON and IGF1R act as members of a redundant signaling network that maintains and compensates signaling input across its cascades." (PMID 32272784, 2020). "Inflammation-condition medium derived from lipopolysaccharide-stimulated HBV+ HCC induces the expression of stemness gene OCT4 and NANOG through an IGF-1R-dependent mechanism, suggesting the possible role of active inflammation in controlling IGF-1R-mediated cancer stemness." (PMID 33511137, 2020). "Studies suggested that IGF1R and EGFR combinatorial therapy might constitute a promising approach for cancer." (PMID 32391121, 2020). "Consistently, IIGFs inhibition have been exploited to overcome BC resistance and improve clinical outcome; however, an ideal way to inhibit IGF-1R, IR-A, and hybrid IR-A in cancer is still lacking." (PMID 33364239, 2020). "Although evident in all cells tested, Golgi-localized IGF-1R is however a particular feature of migratory cancer cells, because cancer cell lines with low or no migratory capacity exhibit little less Golgi-localized IGF-1R." (PMID 33584548, 2020). "Nuclear IGF-1R traffics from the plasma membrane and the levels of IGF-1R nuclear translocation are proportional to ligand-induced kinase activation, because its translocation in cancer cells can be inhibited by xentuzumab, an IGF-1/2 neutralizing antibody, or by inhibition of IGF-1R endocytosis." (PMID 33584548, 2020). "Other data proving that the effect of BMS is independent of IGF-1R levels arise from checking the UALCAN database (a comprehensive web resource for analysis of cancer OMICS data)." (PMID 33322337, 2020). "The co-inhibition of IGF-1R and EGFR might also render cancer cells sensitive to other combined therapies." (PMID 33511137, 2020). "Therefore, IGF-1R knock-down can prevent the up-regulation of MUC1 and epithelial-mesenchymal transition in cancer cells." (PMID 30041514, 2019).
cancer (continued). "Moreover, IGF1R, TNPO1 and FASN are experimentally validated targets for TFAP2A, as annotated by RegNetwork software, and are involved in multiple cancer stemness and drug resistance processes." (PMID 30944375, 2019). "SMAD2/3 is a downstream mediator of TGFBR1 and the activation of AKT is considered the main downstream signal of IGF-1R, both SMAD2/3 and p-AKT participate in the process of cancer progression by promoting cell growth, anti-apoptotic effects, and cell invasion." (PMID 31035970, 2019). "IGF-1R and AKT-GLUT1 axis might be promising targets of miRNAs to affect the progression of cancers." (PMID 31160483, 2019). "Insulin-like growth factor-1 receptor antibodies and mechanistic targets of rapamycin inhibitors have shown some clinical effect in the treatment of recurrent PNET, and these agents can also enhance patient tolerance to cancer treatment." (PMID 31217017, 2019). "Recent studies revealed that blocking IGF-1R pathway, such as small molecule tyrosine kinase inhibitor (TKI, linsitinib) and monoclonal antibodies, can exert attractive effects for the treatment of various types of cancer in clinical trials." (PMID 31467485, 2019). "IGF-1R and INSR are homologous members of the receptor tyrosine kinase superfamily of transmembrane glycoproteins, are widely expressed in normal tissues, and are expressed at high levels in malignant tumors." (PMID 31101650, 2019). "We also noted high baseline expression of several other potential therapeutic targets including VEGFB, TGFB3, PDGFB/PDGFRB, FGFR1 and IGF1R in cancers that did not achieve pCR." (PMID 30967156, 2019). "While compelling preclinical data supported development of IGF-1R targeted drugs as anti-cancer treatments, there have been no unequivocally positive trials." (PMID 31416218, 2019). "It is highly probable that deregulated IR and IGF1R signaling promote development of several cancers but the activity and function of this pathway has not been coherently studied in RCC." (PMID 30929166, 2019). "Other hypermethylated age DMR genes from our data set classified two pathways relevant for growth and development (DCP1B, IGF1R, and FGF18) and cancer progression (TIAM1)—biological processes which has been also mentioned in the literature as epigenetic hallmarks of aging." (PMID 31281827, 2019). "We hypothesized that mTORC1 inhibition activates the IGF-1R/InsR/IRS-1/2 axis in an ER-dependent manner to drive PI3K/AKT and promote cancer cell survival, implicating ER in survival signaling induced by mTORC1 inhibition." (PMID 29507656, 2018). "IGF1R and HMGA2 are important factors that are involved in cancer progression." (PMID 29507664, 2018). "Tissue from WT males showed a higher phosphorylation state of both IR and IGF1R in cancer tissue compared with healthy non-operated esophageal tissue." (PMID 29662006, 2018). "In addition, IGF1R and HMGA2 play an essential role in inducing epithelial-mesenchymal transition (EMT) in cancers." (PMID 29507664, 2018). "Consistent with these biological roles, cells expressing high levels of IGF1R are expected not to die, a quintessential feature of cancer cells." (PMID 29455671, 2018). "The rationale for the development of agents against IGF1R was provided by experimental evidence showing that the receptor is necessary for malignant transformation, while low IGF activity was shown to protect against cancer." (PMID 29731738, 2018). "IGF1R, through ERK1/2 mitogenic pattern activation, seems to be involved in cancer onset." (PMID 29662006, 2018). "Notably, proto-oncogenes such as IGF1R, PI3K, and AKT activate growth signaling and addict cancer cells to nutrient such as glucose and amino acids to meet their high proliferative rate." (PMID 29868472, 2018). "IGF-1 and IGF-1R are known to be abundantly expressed in the PDAC tissue, and activated Insulin/IGF signaling in PDAC cells was found to regulate the basal growth rate of the cancer cells." (PMID 29475434, 2018).